IL2 (interleukin 2)
Diseases named in the same sentence as IL2 in open-access papers (continued):
Sharing a sentence is not in itself a finding about the gene and the disease.
autoimmune disease (continued). "It is noteworthy that in Crohn's disease, which is proposed to be a Th1/Th17-type autoimmune disease, we found significant reduction in plasma levels of IL-2 (Th1 cytokine) and IL-17 after intake of the AbM-based AndoSan extract by the patients." (PMID 21912538, 2011). "In marked contrast to IL-2Rβ−/− mice, the IL-2Rβ transgene restored the normal levels of CD4+CD25+ nTreg and prevented the onset of a fatal autoimmune disease, further reinforcing the notion that IL-2 plays a critical role in the thymic development of nTreg." (PMID 21647403, 2011). "Th1 cells produce interferon- (IFN-γ) and interleukin-2 (IL-2), which are known to be important mediators of organ-specific autoimmune disorders." (PMID 21861931, 2011). "We then move on to describe how this data can be translated to applications for human autoimmune diseases by using IL-2 as a therapeutic agent to restore Treg cell fitness, numbers and functions." (PMID 21059266, 2010). "In the past years, strong genetic and molecular evidence has indicated an essential role for the IL-2/IL-2R pathway in autoimmune disorders." (PMID 21059266, 2010). "The alpha-chain of the receptor for IL2 (IL2RA) is a risk gene for MS and other autoimmune diseases." (PMID 20856809, 2010). "The IL-2-IL-2R pathway plays an essential role in the development of T1 D and other autoimmune disorders in humans and mice." (PMID 21059266, 2010). "This region harbors the interleukin 2 (IL2) and interleukin 21 (IL21) genes and was recently shown to be associated with four autoimmune diseases (Celiac disease, Type 1 diabetes, Grave's disease and Rheumatoid Arthritis)." (PMID 18369459, 2008). "As per the generally-accepted mechanism for the pathogenesis of autoimmune diseases, naive T cells upon activation by antigen produce IL-2 and then undergo clonal expansion and produce pro-inflammatory cytokines (tumor necrosis factor, TNF)." (PMID 16759382, 2006). "Moreover, the clinical safety of the IL‐2:IL‐2 Ab complex has been confirmed in the treatment of autoimmune diseases, hepatitis C vasculitis, and graft‐versus‐host disease." (PMID 41552852, 2026). "IL-2 immunotherapy has been used for autoimmune diseases, neurological diseases and cancers." (PMID 40766255, 2025). "Subjects with SLE and other autoimmune disorders have deficits in IL-2, TGF-β and NK cells." (PMID 41368646, 2025). "Low-dose IL-2 can prevent effector T-cell activation and stimulate Treg cell proliferation at the same time, which has been widely used clinically as a treatment for autoimmune diseases." (PMID 39981233, 2025). "It is well known that IL‐2, through its receptor CD25, is involved in the generation, maturation, and function of Tregs, and a low dose of IL‐2 showed promise as a therapeutic agent in inflammatory and autoimmune diseases, including hepatitis C virus‐induced vasculitis." (PMID 41026618, 2025). "However, clinical trials with low-dose IL-2 to expand functional Tregs in GvHD and autoimmune diseases have given mixed results." (PMID 40799646, 2025). "A dysfunction of IL‐2 and the IL‐2 receptor can lead to excessive immune responses, which may result in numerous autoimmune diseases, like type 1 diabetes, multiple sclerosis, and rheumatoid arthritis." (PMID 40605399, 2025). "Low-dose interleukin-2 (IL-2) has been considered for the treatment of autoimmune diseases." (PMID 39981233, 2025). "However, the results of the study provide evidence for the effectiveness of low-dose IL-2 as a flexible treatment for regulating the immune system, further emphasizing its importance in the overall management of autoimmune diseases." (PMID 39371877, 2024). "Consequently, IL-2 analogs, such as IL-2/antibody complexes and IL-2 mutant proteins, represent promising therapeutic strategies for treating autoimmune diseases." (PMID 39676874, 2024).
autoimmune disease (continued). "IL-2 contributes to activation-induced cell death and the fitness upkeep of Treg cells, playing a crucial role in eliminating self-reactive T cells and thereby preventing autoimmune diseases." (PMID 39169031, 2024). "Furthermore, clinical trials exploring low-dose IL-2 administration in patients with autoimmune diseases have consistently reported an expansion of FOXP3+ Treg populations, although the overall clinical responses have been variable." (PMID 39697333, 2024). "Furthermore, IL-2 has proven safe and effective in managing various autoimmune diseases, including ankylosing spondylitis (AS) and rheumatoid arthritis (RA)." (PMID 38408917, 2024). "Much interest has grown in the treatment of autoimmune diseases with low-dose IL-2." (PMID 38461332, 2024). "Similar variability in Treg expansion and responsiveness may be present in humans, which highlights the need to identify biomarkers that can predict the response to mIL-2/CD25 as well as low-dose IL-2 treatment in T1D and other autoimmune diseases." (PMID 39000278, 2024). "We now know that the pathophysiology of various autoimmune diseases shows a greater degree of similarities and low-dose IL2 shows promising results in autoimmune diseases in general and, in various studies, is found to have a better safety profile as compared to standard therapy alone." (PMID 38646383, 2024). "IL-2 therapy has been explored to selectively expand Regulatory T cells in autoimmune diseases and could be repurposed for musculoskeletal conditions." (PMID 38962732, 2024). "MS patients treated with FTY showed the highest percentage of CD4+ T cells producing GRZB and the lowest percentage of CD4+ T cells producing IL-2, displaying a more cytotoxic profile, that is typically found in autoimmune diseases and, in particular, during MS." (PMID 38553477, 2024). "More importantly, the presence of anti-γc antibody could rescue MSCs during coculture with IL-2/IL-15 prestimulated NK cells, suggesting that suppression of γc activity on NK cells might be a potential way to treat autoimmune diseases." (PMID 38106519, 2023). "Importantly, with the discovery of IL-2 and an increasing knowledge on IL-2 functions, immense research efforts were launched to develop IL-2-based immunotherapies to exploit its properties in cancer and autoimmune diseases." (PMID 37741949, 2023). "Indeed, there is clinical trial data showing that when low-dose exogenous IL2 is administered to patients with autoimmune diseases on days 1–5, plasma Treg levels are augmented by day 8 with no significant increase in IL2 levels." (PMID 37147383, 2023). "Novel low-dose IL2-based therapies for autoimmune diseases have been shown to up-regulate Tregs and may be of use in CHIKV arthritis flares in humans." (PMID 37147383, 2023). "This serves as evidence that IL-2 signaling discrepancies are causative factors in autoimmune diseases and not consequences of disease progression." (PMID 36399073, 2023). "A trial comparing the effect of low-dose IL-2 across 11 autoimmune diseases found an increase in both memory and naïve Treg subsets It remains to be seen whether dosing and treatment regimen can influence the phenotype of expanded Tregs in vivo." (PMID 36399073, 2023). "Several clinical trials are underway to determine whether these drugs present an improved therapeutic avenue for autoimmune diseases than wild type IL-2 to restore immune regulation." (PMID 36399073, 2023). "Low-dose IL-2 has attracted attention in the treatment of autoimmune diseases." (PMID 37596509, 2023). "Low-dose interleukin-2 (IL-2) has been successfully used in a variety of autoimmune diseases." (PMID 36281176, 2022). "In this study, we compared the responses to low dose IL-2 in vitro, of equal numbers of Tregs isolated from patients with autoimmune diseases or allergic asthma to Tregs from healthy controls, to ask if the defect might be in the number of Tregs." (PMID 36569931, 2022).
autoimmune disease (continued). "Disturbed IL-2 pathway has been described in various autoimmune disorders, e.g., RA sufferers display heightened titer of anti-IL-2 antibodies that may affect cytokine bioavailability for Tregs." (PMID 35179632, 2022). "IL-2, the first cytokine that is a potential therapeutic target for the modulation of immune responses, boosts the immune response in cancer and autoimmune diseases and promotes the generation of Treg cells, B cell proliferation, the secretion of antibodies and macrophage activation." (PMID 35082324, 2022). "Two such strategies, low-dose interleukin-2 (IL-2) administration and Treg cell adoptive transfer, have received much attention in recent research and have been tested in clinical trials for several autoimmune diseases." (PMID 36591309, 2022). "Therefore, low doses of IL-2 have been used in the treatment of systemic lupus erythematosus, type 1 diabetes, and other autoimmune diseases." (PMID 36244973, 2022). "Interleukin-2 (IL-2) and the high-affinity IL-2 receptor (IL-2R) are essential for the survival of regulatory T cells (Tregs) which are the main players in immune tolerance and prevention of autoimmune diseases." (PMID 35526080, 2022). "IL2 labelled with 123I (123I-IL2) and 99mTc (99mTc-IL2) has been used in vivo to detect activated lymphocytes in different autoimmune diseases, such as Coeliac disease, IDDM, Hashimoto’s thyroiditis, Takayasu’s arteritis, multiple-autoimmunity and, recently, to detect immune infiltration on cancer." (PMID 35955984, 2022). "Together, these data indicate that administration of IL-2 could shape the bacterial community in mice with autoimmune disease and simultaneously suppress inflammation with the formation of plasticity of the host immune system." (PMID 35360108, 2022). "Rather than immunodeficiency, diminished IL-2 production is associated with autoimmune disease development in mice and humans, highlighting the critical role of this cytokine in maintaining immunological tolerance." (PMID 33986755, 2021). "This paradoxical function of the IL-2 – IL-2R pathway may be an attractive therapeutic target for autoimmune diseases such as MS." (PMID 35005590, 2021). "IL-2 therapy has also been successfully tested in other lesser studied autoimmune diseases." (PMID 35069220, 2021). "Recently, due to the important role of IL-2 in promoting the differentiation of Treg cells and inhibiting the differentiation of Th17 cells, there is growing interest in using IL-2 for the treatment of autoimmune diseases." (PMID 33816637, 2021). "Furthermore, a better understanding of the endogenous cytotoxic profiles in patients with T1D and other autoimmune diseases would be also valuable in order to anticipate the effect of IL-2 treatment in future clinical trials." (PMID 34324441, 2021). "Similarly, most clinical trials of Ld-IL2 therapy in other autoimmune diseases measured CD4+ T cells subsets, particularly TREG cells as the primary endpoints, including GVHD, Vasculitis, type 1 diabetes and Sjögren’s syndrome." (PMID 34618873, 2021). "The use of a low dose of recombinant IL-2 allowed induction of immune tolerance and proliferation of T lymphocytes, which results in the suppression of unwanted immune responses and a therapeutic effect in some autoimmune diseases." (PMID 34442052, 2021). "Eventually, this review may launch broad interest in the IL-2 – IL-2R pathway propelling further research in autoimmune diseases, including MS." (PMID 35005590, 2021). "In addition, it has been reported that the imbalance between Treg and Tfh cells is a characteristic of autoimmune diseases and is dependent on homeostatic cytokines, including IL-2." (PMID 34130625, 2021). "As IL-2 and IL-2R knockout mice develop severe autoimmune disease, such models cannot be used to assess whether IL-2 is required for Mtb protection." (PMID 32678272, 2021).
autoimmune disease (continued). "Indeed, it has been shown that long-term, low-dose IL-2 therapy preferentially stimulates Treg cells due to their constitutive high expression of trimeric IL-2R and can be used for treatment of autoimmune diseases and delaying allograft rejection." (PMID 34932467, 2021). "We hypothesized that IL-2-REH-mediated expansion of Tregs might have utility in the suppression of immune activation in the setting of autoimmune disease." (PMID 34003116, 2021). "Low-dose IL-2 (Ld-IL2) therapy emerges as a new treatment for a wide range of autoimmune diseases." (PMID 34618873, 2021). "In summary, the inhibitory effects of IL-2 in Th17 cells, and its subsequent effects on Auto-Ab responses and systemic inflammation, need to be evaluated when considering IL-2-based therapies for the treatment of autoimmune disorders." (PMID 33986755, 2021). "It has been shown that IL-2/JES6 could be used for treatment of various autoimmune diseases and to facilitate long-term acceptance of allografts without the need for immunosuppression." (PMID 34932467, 2021). "Recent studies have indicated that treatment with a low-dose IL-2 induces immune tolerance resulting in the suppression of an unwarranted immune responses and suggests that it may be a possible treatment of certain autoimmune disorders." (PMID 34685775, 2021). "Moreover, ADT has been revealed to reduce Th1 and Th17 responses and also the concentration of inflammatory cytokines involved in several autoimmune diseases, including IL-1β, IL-2, tumor necrosis factor (TNF)-α and interferon (IFN)-γ." (PMID 32580478, 2020). "In the absence of IL-2 signals, Treg cell number declines substantially, whereas Th17 cell number increases, leading to an enhanced susceptibility to autoimmune disease and inflammatory disorders." (PMID 33211703, 2020). "In addition, neutralization of circulating IL-2 by anti–IL-2 monoclonal antibodies inhibits Tregs proliferation and triggers a wide range of organ specific autoimmune diseases." (PMID 32676072, 2020). "Th1 cells secrete IL-2, INF-γ, and TNF-α; these can stimulate B lymphocytes to produce a large number of autoantibodies and induce the production of TGF-β, thus making the body susceptible to autoimmune diseases." (PMID 32565866, 2020). "IL-2 has the potential to expand Tregs in vivo in autoimmune disease patients." (PMID 32977677, 2020). "IL-2 signalling is critical for the function of regulatory T cells (Tregs), a type of suppressive immune cell, which plays an indispensable role in maintaining immune homeostasis and prevention of autoimmune diseases." (PMID 33193091, 2020). "A recent report demonstrated the potential of IL-2 to enhance Treg therapy in autoimmune disease." (PMID 32664850, 2020). "This limitation may restrict the efficacy of FPs for direct clinical application as a low-zone IL-2 therapy in autoimmune disease, because many autoimmune diseases are marked by relatively high IL-2 concentrations in target tissues." (PMID 33072087, 2020). "Conversely, if CTL-derived exosomes are indeed involved in autoimmune disease, neutralization of IL-2 could become an effective method to dampen exosome function." (PMID 31275303, 2019). "For example, in psoriasis, a long-lasting autoimmune disease characterized by patches of abnormal skin, increased IL-2 levels may mediate pruritus; furthermore, serum IL-2 levels are significantly higher in patients with psoriasis than in healthy subjects." (PMID 31998324, 2019). "Patients with autoimmune diseases such as type 1 diabetes, rheumatoid arthritis, and systemic lupus erythematosus, compared with healthy individuals, have a genetically determined low IL-2 production, which reduces their Treg fitness." (PMID 29615964, 2018). "The contribution of Tregs in autoimmune disease has opened up a new therapeutic avenue based on restoring a healthy balance between Tregs and effector T-cells, such as Treg-based cellular transfer or low-dose IL-2 modulation." (PMID 30374354, 2018).
autoimmune disease (continued). "Interestingly, the proof-of-concept trial of ld-IL-2 in an autoimmune disease showed not only that it safely activates Tregs but also that it has an overall anti-inflammatory effect." (PMID 29615964, 2018). "There are evidences that anti-IL-2 antibodies (Abs) are present in subjects affected by autoimmune diseases and may be responsible for alterations in regulatory T cell responses." (PMID 29379122, 2018). "The role of IL-2, and likewise of Tregs, in autoimmune diseases was recently further highlighted by the meta-analysis of a shared genetic architecture across 10 pediatric autoimmune diseases which revealed a central role of the IL-2 pathway." (PMID 29615964, 2018). "Thus, IL-2 therapy is a promising avenue for expanding Treg cells and improving clinical outcomes for patients with autoimmune disease and trials are ongoing in connective tissues diseases including systemic sclerosis (TRANSREG study NCT01988506)." (PMID 30374354, 2018). "Interestingly, TNF-α, IL-12p70, IFN-γ and IL-2 belong to the cytokines T Helper 1 (Th1) that mediate the development of organ-specific autoimmune disease and are considered as positive effectors of inflammation." (PMID 30018377, 2018). "However, although hypoproliferation and reduced production of IL2 in response to antigen stimulation are the hallmarks of T cell tolerance, auto‐reactive T cells from autoimmune disease patients rarely display hyperproliferation in response to autoantigens." (PMID 29314730, 2018). "IL-2 might indeed become a prime candidate for the treatment of a broad range of autoimmune diseases." (PMID 29527328, 2018). "This may be of importance, as IL-2 is known to prevent autoimmune disease by promoting the differentiation of naïve T cells into regulatory T cells." (PMID 30347791, 2018). "The discovery that such adverse reactions could be prevented when IL-2 was administrated as immune complex bound to anti-IL-2 mAb opened up new therapeutic approaches for the treatment of autoimmune diseases like SLE." (PMID 29670626, 2018). "This could be important because the use of low-dose IL-2 therapies is being tested in various autoimmune diseases." (PMID 29323192, 2018). "Furthermore, in humans, variation of genes in the IL-2 pathway, for example IL2RA encoding CD25, alters susceptibility to autoimmune diseases, including T1D." (PMID 28284938, 2017). "Among pathways shared by any two groups, we find the IL pathways are informative for shared disease features: the IL23 and IL27 pathways are common to both autoinflammatory and mixed diseases, while the IL2 pathway is common to both autoinflammatory and autoimmune diseases." (PMID 27964755, 2016). "Major depressive disorders have been reported in patients being treated with the recombinant cytokines interleukin-2 (IL-2) and interferon-α (IFN-α), and chronic inflammatory diseases such as coronary artery and autoimmune diseases have been associated with an increased incidence of mood disorders." (PMID 28393111, 2016). "This unexpected finding was soon ascribed to the critical function of IL-2 for regulatory T cells (Tregs) which prevent severe autoimmune diseases throughout the lifespan of mice (and humans) by suppressing auto-reactive T cells that escape thymic negative selection." (PMID 26731275, 2016). "Recently, selective improvement of the levels and function of Tregs has been demonstrated as a result of the low-dose IL-2 immunotherapy in the experimental model of autoimmune disorders as well as in the phase I/II clinical trial in patients with type 1 diabetes." (PMID 25145773, 2015). "The potentiation of TCR-stimulated IL-2 transcription that results from blocking Gβγ in CD4+ T helper cells could have applications for autoimmune diseases." (PMID 25629163, 2015). "All these studies emphasized the relevance of IL-2 dosing and possible interactions with other immunomodulatory drugs, which alone could improve the course of autoimmune disease." (PMID 25322151, 2014).